POTEC (POTE ankyrin domain family member C)
Synonyms: POTE-18; A26B2; POTE18; DKFZp686J0529; CT104.6
Tractability: PROTAC: ubiquitination databases record sites on it.
Gene: Protein-coding gene on chromosome 18 (14,507,339 to 14,543,600, reverse strand). Ensembl gene ENSG00000183206.
Genetic constraint (gnomAD): Loss-of-function variants: 27 observed, 45.19 expected, observed/expected ratio (o/e) 0.6, 90% interval 0.44 to 0.82. The synonymous counts are far from expectation, so gnomAD's model fits this gene poorly and the ratio says little. Missense variants: 414 observed, 528.08 expected, observed/expected ratio (o/e) 0.78, 90% interval 0.72 to 0.85. Synonymous variants: 140 observed, 180.41 expected, observed/expected ratio (o/e) 0.78, 90% interval 0.68 to 0.89.
Homologues: Paralogues in human: POTEB3 (96% identical), POTED (96% identical), POTEB (89% identical), POTEB2 (89% identical), POTEI (87% identical), POTEF (87% identical), POTEE (87% identical), POTEJ (82% identical), POTEH (82% identical), POTEG (81% identical), POTEM (81% identical), POTEA (57% identical), and 2 more.
Diseases named in the same sentence as POTEC in open-access papers:
POTEC is named in the same sentence as 6 diseases in open-access papers, as found by Europe PMC text mining. Sharing a sentence is not in itself a finding about the gene and the disease. The quoted sentences say what the papers report.
cervical carcinoma (1 paper, 2021). A carcinoma arising from either the exocervical squamous epithelium or the endocervical glandular epithelium. "The increased sample size enabled identification of SMGs previously unreported in cervical carcinoma including NBPF10 (8%), RANBP2 (6%), MSN (6%), KRT8 (6%), POTEC (6%), ZC3H11A (4%), BMS1 (4%), GPX1 (3%), OTOP1 (3%), DNAH12 (2%), COIL (2%), TBC1D26 (2%), SPRED3 (2%), FAM115A (2%), and ARIH1 (1%)." (PMID 34620846, 2021).
colon cancer (1 paper, 2019). "POTEC is a member of the highly homologous POTE family which are expressed in multiple cancer types including colon cancer." (PMID 30952955, 2019).
ovarian carcinoma (1 paper, 2025). A malignant neoplasm originating from the surface ovarian epithelium. "In a similar study with the GeCKO library in the A2780 and SKOV3 ovarian cancer cell lines, ZNF587B, TADA1, SEMA4G, POTEC and USP17L20 were identified as candidate genes; among these, loss of ZNF587B and SULF1 gene expressions were associated with cisplatin resistance." (PMID 40242936, 2025).
prostate carcinoma (1 paper, 2025). A carcinoma that arises from epithelial cells of the prostate gland. "Cluster C2, associated with primary prostate cancer, expressed genes like MMP13 and POTEC." (PMID 40165961, 2025).
tumor (1 paper, 2018). "We also identified different tumor clusters characterized by specific POTE expression patterns (right labels), and the most prominent clusters were characterized by high expression of POTEC and/or POTE-actin genes." (PMID 30459449, 2018).
POTEC also shares sentences with these, for which no sentence is quoted: cancer (1 paper).